IFNG (interferon gamma)
Diseases named in the same sentence as IFNG in open-access papers (continued):
Sharing a sentence is not in itself a finding about the gene and the disease.
asthma (continued). "Given that asthma can induce a mixed Th1/Th2 phenotype response, we also assessed airway IFNγ levels—the untreated airways contained quite modest levels of IFNγ and DC10 treatment did not affect this in a statistically significant manner (p>0.05)." (PMID 33793599, 2021). "Quercetin is another potent anti-inflammatory flavonoid that ameliorates asthma by reducing the eosinophilic mediators and type 2 helper cytokines and increases interferon gamma (IFNγ)." (PMID 33628717, 2021). "RG-II isolated from Panax ginseng induced the Th1/Th2 immune response and IFNγ expression in mice with ovalbumin-induced asthma, while IL-4 and GATA3 expression and eosinophil populations were decreased in the bronchoalveolar lavage fluid." (PMID 32326081, 2020). "In allergic disease such as asthma and allergic rhinitis, interferon gamma/interleukin 4 (IFN-γ/IL-4) cytokines or Th1/Th2 balance shifted toward IL-4 or Th2 lymphocyte." (PMID 31156785, 2019). "There is evidence that leptin can upregulate cytokines such as IFNγ and IL-17 in asthma and can both promote and inhibit Th2 effector functions in vitro and in type 2 diseases such as asthma and allergic rhinitis." (PMID 30978945, 2019). "Low doses of IFNγ have been shown to have anti-inflammatory effects in asthma and EAE animal models as well as in human." (PMID 31750310, 2019). "Although IRF5−/− mice subjected to the severe asthma model displayed lower IFNγ and IL-17 responses and lower neutrophil numbers, they had higher Th2 responses with higher eosinophil numbers." (PMID 29572536, 2018). "While intranasally administered streptomycin had little effect on asthma, it exacerbated hypersensitivity pneumonitis and increased IL-17 and IFNγ expression in the lung." (PMID 28596951, 2017). "To investigate the anti-asthmatic effects of picroside II, we determined the levels of inflammatory cytokines, such as Th1 cytokine (IFNγ), Th2 cytokines (IL-4, IL-5, and IL-13), and asthma related cytokine (IL-33) in the BALF using ELISA kit." (PMID 27870920, 2016). "ELISA analysis showed that picroside II down-regulated the levels of Th2-related cytokines (including IL-4, IL-5, and IL-13) and asthma-related mediators, but it up-regulated Th1-related cytokine, IFNγ in BALF." (PMID 27870920, 2016). "Dexamethasone IC35 and IC50 values for IL-17 and IFNγ were lower in healthy subjects compared to asthma." (PMID 27716212, 2016). "The interferon-gamma protein is a potent activator of macrophages, which coupled with the fact that the majority of key genes for this metagene are associated with its left branch, suggests that macrophage activation maybe an important driver for the Leaf 5 asthma endotype." (PMID 25643280, 2015). "One study linked differential DNA methylation in the vicinity of two candidate genes (FOXP3 and IFNγ) with asthma in a study of N = 21 asthma-discordant adult monozygotic (MZ) twin pairs." (PMID 26691723, 2015). "In this line, differential methylation of FOXP3 and IFNγ promoter regions was demonstrated in isolated peripheral regulatory and effector T cells from 21 monozygotic twin pairs discordant for asthma (age range 9 to 76 years)." (PMID 26052354, 2015). "IFNγ has been found at elevated levels in the sera of patients with adult acute severe asthma, and IFNγ+ cells become upregulated in correlation with eosinophil infiltration in allergic subjects." (PMID 25426119, 2014). "IFNγ methylation also has been shown to vary by asthma diagnosis among monozygotic twins consistent with mediation by environmental exposure." (PMID 24891923, 2014). "The IL-4 and IFNγ levels of the asthma group were significantly higher and lower than that of control mouse group, respectively (p < 0.01)." (PMID 25177863, 2014). "In agreement with the findings in human asthma, it was shown that both IFNγ and LPS contribute to airway inflammation and airway hyperreactivity in a mouse model of asthma." (PMID 23533311, 2013).
asthma (continued). "The proinflammatory cytokines tumor necrosis factor α (TNFα) and interferon γ (IFNγ) are increased in asthma and have been shown to contribute to apoptosis at the airways." (PMID 24303189, 2013). "Bronchial asthma patients display hypermethylation of the IFNG gene in CD4+ T cells following allergen challenge which correlated with decreased IFNG expression." (PMID 24244422, 2013). "In severe asthma, the largest change (110-fold) is observed in Ifnγ expression followed by Il13, Il2, Il4, Il10, Il6, Il5, and Tnfα, respectively." (PMID 23781124, 2013). "Fully in line with this finding, we here show that sitostanol induced a Th1 response in PBMCs from asthma patients, indicated by an increase in the concentration of cytokines IL-2 and IFNγ." (PMID 23091602, 2012). "In conclusion, we observed an association between maternal PAH exposure and promoter methylation of an asthma-related gene, IFNγ, in cord white blood cells from 53 children in our study cohort." (PMID 22562770, 2012). "Stimulated PBMCs from asthma patients clearly showed higher IL-13 and IL-5 and lower IFNγ responses as compared to those of healthy controls." (PMID 23091602, 2012). "The observed insensitivity of IFNγ- or cytomix-induced CXCL10 to current asthma medications emphasizes the need for novel compounds that can inhibit these nonresponsive pathways." (PMID 23034049, 2012). "Sitostanol significantly increased IFNγ production by 4493 pg/mL (p<0.05) when compared to cholesterol, but only in PBMCs from asthma patients." (PMID 23091602, 2012). "Our investigation demonstrates that an increase in methylation of CpG sites within FOXP3 and IFNγ results in decreased protein expression and is associated with impaired T cell function that vary by SHS exposure and asthma diagnosis among MZT." (PMID 23226205, 2012). "Further, asthma is largely characterized as a Th2 mediated disease, accompanied by high IL-4 and IL-5 production and low IFNγ." (PMID 21345191, 2011). "IL-12 (p40), IL-5, and IFNγ/IL-5 showed differences between the extrinsic and intrinsic asthma phenotype." (PMID 21179211, 2010). "In our studies, not only did hMSC in children decrease the pathology and inflammation in the acute murine asthma, but there was a significant decrease in lung IFNγ levels consistent with decreased immune activation." (PMID 20974000, 2010). "Decreased expression of immuno-regulatory cytokines, including IL-12, IL-18, or interferon gamma, can strengthen the inflammatory process and play regulatory roles in asthma by modifying Th2 lymphocyte responses." (PMID 16083514, 2005). "In addition, in the top DEGs in severe compared to mild asthma showed neutrophil degranulation, neutrophil activation involved in immune response, and response to interferon gamma were significantly upregulated." (PMID 40313552, 2025). "Moreover, IFNG is critical for regulating asthma airway hyperreactivity, and EGFR can affect distal airway epithelial responses to allergies and manage airway epithelial inflammation." (PMID 40420184, 2025). "Although one of Th1 cell’s functions has been commonly known to modulate the activation and level of Th2 cell from the recent study Th1 cell-related cytokine, interferon gamma (IFN-γ) had been reported to play keeping the inflammatory response in asthma with Th2 cell-related cytokines." (PMID 40323927, 2025). "Taken together, several lines of evidence support a role for IFNγ and IL‐17 in type 2‐low asthma." (PMID 40016948, 2025). "Some pro-inflammatory cytokines relevant to asthma are interleukin (IL)-4, IL-13, IL-17, and IFNγ." (PMID 39197446, 2024). "We did not identify any significant heritability enrichment for any of the stimuli gene sets for the asthma-associated traits tested here, nor for the control traits (except for genes upregulated by IFNγ for RA)." (PMID 39197446, 2024).
asthma (continued). "However, there is also prior evidence that up to one-third to half of patients with severe asthma may have a type 1 inflammatory signature in their airways which is associated with more severe disease and corticosteroid resistance and potentially involving the interferon-gamma/CXCL10 axis." (PMID 38710930, 2024). "Interestingly, we observed elevated frequencies of IFNγ+IL-5+, IFNγ+IL-9+, and IFNγ+IL-13+ double-producing Tc cells, supporting type-2 skewing of IFNγ+ Tc1 cells in asthma." (PMID 37612281, 2023). "While the pathways that mediate corticosteroid insensitivity in asthma remain poorly defined, recent studies suggest that enhanced Th1 pathways, mediated by TNFα and IFNγ, may play a role." (PMID 35578269, 2022). "Genes IFNG and MMP9 were associated with Airway Inflammation in Asthma." (PMID 35812753, 2022). "TNFα and IFNγ are known to synergistically induce the production of several pro-inflammatory cytokines and chemokines, including CXCL10, a key T lymphocyte chemoattractant implicated in severe asthma." (PMID 35578269, 2022). "For example, TNF synergizes with IFNγ to mediate steroid-resistance in asthma." (PMID 35387021, 2021). "Although the overall frequency of B cell was comparable between the BALFs and lungs with eosinophilic (Alum/OVA) or neutrophilic (CFA/OVA) asthma, the IFNγ production of B cells from lungs with neutrophilic asthma was significantly higher than in the neutrophilic asthma group." (PMID 34061861, 2021). "IFNγ has been identified as a driver of severe, steroid unresponsive asthma." (PMID 33101299, 2020). "One and 5 μg/ml BioPM collected from chicken, goat and pig farms induced the production of IFNγ, IL-10, IL-1β and TNFα by PBMCs from stable asthma patients and healthy volunteers in an apparent concentration-dependent manner (except for TNFα production induced by BioPM from the goat farm)." (PMID 32620109, 2020). "Still, the pathophysiological effect of enhanced IFNγ responses is unknown, although we have shown before that the IFN response during rhinovirus-induced loss of asthma control correlates with eosinophilic inflammation and drop in FEV1." (PMID 32620109, 2020). "We did, however, detect increased IFNγ levels during loss of asthma control after 1 but not after 5 μg/ml pig farm exposure, which suggests a lower threshold for IFNγ induction by PBMCs from these patients." (PMID 32620109, 2020). "While no clear differences were observed when comparing AMs from asthma patients to HCs, AMs from steroid-resistant asthma patients displayed a decreased M-dex signal and increased M-LPSearly, M-IFNγ, and M-LPS+IFNγ signal relative to steroid sensitive asthma AMs." (PMID 31921150, 2019). "Interleukin-10 (IL10) and interferon gamma (IFN-γ) are protective cytokines against asthma." (PMID 32641957, 2019). "Typically in asthma, cytokines released by Type 2 T helper (Th2) cells including interleukin-4 (IL-4), interleukin-5 (IL-5), and interleukin-13 (IL-13) as well as cytokines released by Type 1 T helper (Th1) cells such as interferon-gamma are considered to be the main cytokines triggered in asthma." (PMID 30333747, 2018). "Interestingly, increased levels of IFNγ are observed in patients with severe, glucocorticoid-resistant asthma—the same category of patients that have decreased PP2A expression." (PMID 28267764, 2017). "Our study specifically focused on IFNγ as a candidate gene, hypothesizing that this gene would lie in the mechanistic pathway linking dietary intake to asthma health outcomes in children." (PMID 28261276, 2017). "Asthma is phenotypically characterized by a shift toward type 2 T helper (Th2) polarization and consequently type 1 T helper (Th1) cell cytokines such as interferon gamma (IFNγ) play a critical role as counter regulators in the allergic asthma pathway." (PMID 28261276, 2017). "In addition we measured LINE-1 and IFNγ (CpG-54 and -186) methylation levels to identify pathways whereby diet influences the health among children with asthma." (PMID 28261276, 2017).
asthma (continued). "It is known that IFNγ is reduced in many cases of asthma and in cases of endotoxin exposure." (PMID 27375768, 2016). "Tofacitinib plus dexamethasone produced a greater effect than dexamethasone alone, with an additive effect on the inhibition of IL-13 and IFNγ production from asthma and healthy cells; this additive effect on IL-13 from healthy cells was only apparent at low dexamethasone concentrations." (PMID 27716212, 2016). "However, there is also evidence of an increased T-helper 1 (TH1) response in asthma, with IFNγ overproduction, and a role for T-helper 17 (TH17) cells in promoting neutrophilic inflammation in asthma." (PMID 27716212, 2016). "While the exact mechanism involved is unknown, the increase in TH2 cytokines in the BAL fluid of γc−/− and γcxRAG2−/− mice, together with the reduction in IFNγ may contribute to this exaggerated asthma response." (PMID 23940740, 2013). "If lack of IFNγ production by NK cells was causing the enhanced asthma phenotype observed in γc deficient mice, then we would expect to see the same phenotype in NK cell depleted RAG2−/− mice." (PMID 23940740, 2013). "Thus, both the presence of M1 skewing factors (IFNγ, TNFα, or LPS) and the proinflammatory mediators released by M1 macrophages can contribute to asthma." (PMID 23533311, 2013). "However, in PBMCs from asthma patients the increase in IFNγ correlated significantly with IL-2 (ρ = 0.648 p<0.05), but not with IL4 or IL-13, showing a Th1 dominant shift in response to sitostanol." (PMID 23091602, 2012). "As we also observed decreased Teff function from asthmatic twins, we wanted to assess whether IFNγ expression varied by asthma." (PMID 23226205, 2012). "To address this hypothesis, we conducted cellular and molecular studies at the functional, protein, transcript and epigenetic level of FOXP3 and IFNγ in purified T cell subsets among MZT discordant for asthma." (PMID 23226205, 2012). "We also chose to measure DNA methylation of two representative asthma genes, namely IFNγ and iNOS." (PMID 22414378, 2012). "Using buccal cells, we hypothesized that DNA methylation in promoter regions of two asthma genes, inducible nitric oxide synthase (iNOS) and interferon γ (IFNγ), can vary over several days." (PMID 22414378, 2012). "Furthermore, a molecular phenotype characterized by the presence of CXCL1, RANTES, IFNγ, IL-12 and IL-10 separated children with severe asthma from those with moderate asthma." (PMID 22168152, 2011). "In addition to understanding how hMSCs regulate in vivo systemic and localized IFNγ/IL-1β levels, our focus will also include factors secreted by the hMSCs or by the host in response to MSCs, which alter the course of asthma." (PMID 20974000, 2010). "To test our hypothesis we measured serum concentrations of eleven cytokines and chemokines that were recently described to play an important role in asthma pathogenesis: IL-4, IL-5, IL-8, IL-10, IL-12 (p40), IL-13, IL-17, TNFα, GM-CSF, eotaxin, and IFNγ." (PMID 21179211, 2010). "Inhaling irritants strongly contributes to the development of asthma through two main mechanisms: firstly, it induces the death of AECs, and secondly, it triggers the activation of various inflammatory mediators such as interleukin-17 (IL-17) and interferon-gamma (IFN-γ)." (PMID 39538061, 2024). "However, in our model, IFNγ-producing B cells showed a protective role in allergy and asthma." (PMID 37759658, 2023). "In addition, although the direct contribution of IFNγ has not been examined in these models of SSRNAD, IFNγ has been implicated in severe asthma in humans and experimental mouse models." (PMID 36776857, 2023). "However, type 1 and 17 cytokines (i.e. IFNγ and IL-17) are elevated in T2-lo asthma." (PMID 36776857, 2023). "As with our earlier asthma study, this could be investigated using anti-IFNγ antibody treatment." (PMID 38077318, 2023).
asthma (continued). "Furthermore, Th1 type immune response, such as interferon-gamma (IFN-γ)-related IP-10 production, may be linked to the severity of asthma in humans via the enhancement of eosinophilic inflammation." (PMID 35625578, 2022). "Interestingly, in the absence of asthma, the overweight or obese children were instead susceptible to hypermethylation of IFNγ CpG−186 following V exposure." (PMID 28424066, 2017). "However, the associations of FeNO with DNA methylation of other asthma gene promoters (i.e., IFNγ and ARG2) were not significant in adjusted models (p > 0.05)." (PMID 28588744, 2017). "Finally, a series of studies using either a ragweed or dust mite-sensitized mouse model of asthma showed that pre-treatment with a DNA adjuvant known to result in Th1 biased immune status with marked overproduction of IFNγ resulted in an ameliorated lung inflammatory phenotype." (PMID 28261276, 2017). "Although the direction of the sex- and age-specific methylation differences in ZPBP2 is opposite to that of IFNγ, both our and the Naumova studies highlight the significance of age and sex in DNA methylation that may modify genetic effects in diseases like asthma." (PMID 24891923, 2014). "Neutrophilic infiltration is driven by increased IFNγ and/or IL‐17A production, and IFNγ and IL‐17A were increased in bronchoalveolar lavage (BAL) fluid and in CD4 and CD8 T cells of patients with severe asthma compared to controls or milder asthma phenotypes." (PMID 41508394, 2026). "In contrast, IFNG and FOXP3 were significantly upregulated in the control group, suggesting potential differential roles for these proteins in asthma development." (PMID 40309741, 2025). "Asthma patients with airway type 2 high inflammation (e.g., IL-13) demonstrate more eosinophils and airway hyperresponsiveness (AHR) with less interferon gamma." (PMID 40170850, 2025). "Whole-transcriptome sequencing identified key inflammatory genes, such as IL1B, CCL17, and MUC5AC, that were upregulated in asthma patients, while immune regulatory factors like FOXP3 and IFNG were higher in healthy controls." (PMID 40309741, 2025). "Genes such as IL1B and CCL17 exhibited significantly upregulated expression in the patient group, while others, like IFNG and FOXP3, were markedly downregulated (p < 0.05), suggesting their potential roles in asthma pathogenesis." (PMID 40309741, 2025). "On the contrary, Th1 cells can release IL-2, IL-12, and interferon-gamma (IFN-γ), among which the characteristic cytokine IFN-γ plays an inhibitory role in asthma by hindering the aggregation of eosinophils and reducing the expression of immunoglobulin." (PMID 39444792, 2024). "Different to glucocorticoid treatments, GGsTop was able to suppress expressions of IFNγ, TNFα and MCP-1, the three key factors in steroid resistant asthma." (PMID 37377967, 2023). "Effects of TNFα and IFNγ enhanced several pro-inflammatory genes and pathways related to ASM and its contributions to asthma pathogenesis, which persisted in the presence of corticosteroids." (PMID 35578269, 2022). "Fourteen core targets including IL4, IFNG, and MMP9 were identified for the treatment of asthma by SYD." (PMID 36212941, 2022). "When the expression of CD38 was examined in ASM cells, a molecule involved in AHR and airway inflammation in asthma, GC was unable to inhibit CD38 expression when cells were treated with the combination of TNFα and IFNγ." (PMID 36012240, 2022). "Th1 cytokines, TNFα and IFNγ, have substantial pro-inflammatory effects on ASM that contribute to airway inflammation, hyperresponsiveness, and remodeling in asthma, however little is known about their combined effects on ASM gene expression." (PMID 35578269, 2022). "IL4 and exhaled nitric oxide, combined with 8-isoprostane and interferon-gamma (IFN-ɤ), were effective markers for asthma control." (PMID 36140412, 2022).